TLR9 (toll like receptor 9)
Diseases named in the same sentence as TLR9 in open-access papers (continued):
Sharing a sentence is not in itself a finding about the gene and the disease.
steatosis (15 papers, 2011 to 2025). Increased lipid within the cytoplasm of cells. "In fact, TLR4- or TLR9-deficient mice given HFD or choline-deficient diet were protected from hepatic steatosis and inflammation." (PMID 36875849, 2023). "The present study demonstrated, for the first time, that whole-body TLR9 deficiency exacerbates chronic alcohol-induced liver injury, steatosis, oxidative stress, mitochondrial dysfunction, and apoptosis." (PMID 34262465, 2021). "Indeed, TLR4- or TLR9-deficient mice treated with HFD or a choline-deficient diet were protected from steatosis-related liver failure and inflammation." (PMID 39997751, 2025). "TLR9 signaling plays a crucial role in the progression of fatty liver disease by promoting inflammation, steatosis, and fibrosis through its interactions with hepatocytes, Kupffer cells, and hepatic stellate cells." (PMID 39158380, 2025). "Some preclinical studies have highlighted a marked involvement of TLR4 and TLR9 in the development of steatosis, inflammation, and fibrosis." (PMID 39997751, 2025). "TLR9 expression in the liver is positively correlated with the severity of steatosis in patients with non‐alcoholic fatty liver disease (NAFLD), suggesting its role in pathogenesis." (PMID 39158380, 2025). "TLR-2, TLR-4, and TLR-9, which are predominantly expressed in KCs, are critical in the pathogenesis of steatosis, inflammation, and fibrosis in several diet-induced mouse models of NAFLD and NASH." (PMID 39300994, 2024). "Some preclinical studies have shown a marked involvement of TLR4 and TLR9 in the development of steatosis, inflammation and fibrosis." (PMID 36875849, 2023). "There was also an increase of mRNA levels of inflammatory pathway genes toll-like receptor 9 (Tlr9) and tumor necrosis factor (Tnf-α) with steatosis." (PMID 34257827, 2021). "When they co-stimulated T-cells via TLR9, the cells from the patients with simple steatosis produced a limited number of IFN-γ producing CD8+ T cells compared with the T cells from patients with NASH." (PMID 33584545, 2020). "Despite exhibiting equivalent levels of steatosis, hardly any inflammation was observed in the TLR9 KOs fed the atherosclerotic diet." (PMID 33584545, 2020). "Recent studies have shown that the level of hepatocyte-derived mitochondrial DNA is elevated in plasma samples obtained from mice and NASH patients, and it has the ability to toll-like receptor 9 (TLR9) activation resulting in steatosis, hepatocyte injury, and fibrosis." (PMID 36718239, 2022). "TLR9 is a receptor for bacterial DNA, in particular for the unmethylated CpG motif, which is increased in NASH models; the activation of TLR9 signaling on Kupffer cells induces the production of proinflammatory cytokine, such as IL-1β leading to steatosis and inflammation." (PMID 29563854, 2018). "Previous research has shown that TLR9 signaling promotes KC production of interleukin-1β (IL-1β) in a mouse model of NASH, contributing to steatosis, inflammation, and fibrosis." (PMID 39300994, 2024). "The expression of TLR4 and TLR9 is higher in the liver of patients with MASH (but not if only steatosis is present), and diet-induced experimental MASH is less severe in mice made genetically deficient in TLR9." (PMID 38921459, 2024). "Although the biological significance of HBV-induced TLR9 impairment remains unclear, recent data suggest that TLR9 stimulation may induce liver damage (inflammation, fibrosis, steatosis), involving non-parenchymal liver components (stellate, Kupffer and sinusoidal endothelial cells)." (PMID 22046272, 2011). "In liver, Geoffrey Farrell’s lab at the Australian National University found that TLR9 expression is significantly upregulated in patients with biopsy-verified NASH, but not in liver with bland steatosis." (PMID 33584545, 2020).
allergic asthma (14 papers, 2012 to 2024). A asthma with a basis in a pathological type I hypersensitivity reaction. "During swollen A. fumigatus induced allergic asthma, TLR-9-deficient mice are more susceptible and show increased fungal growth." (PMID 31824491, 2019). "In an experimental model utilizing mice, IL-2 is significantly elevated and can exacerbate allergic asthma through the toll-like receptor 9-IL-2 axis." (PMID 38967887, 2024). "In future, we need to analyze the role of γδ T cells for HDM-induced allergic asthma in Tlr9−/− mice." (PMID 33093516, 2020). "Blockade of TLR9 by treatment with TLR9-inhibitory-antibody, NaR9, effectively suppressed the development of allergic asthma pathology." (PMID 33093516, 2020). "To evaluate the therapeutic effects of TLR9 inhibitory antibody, NaR9 in allergic asthma, we gave NaR9 to allergic asthma model mice." (PMID 33093516, 2020). "Next, we examined TLR9 expression on lung-infiltrating immune cells, granulocytes, and alveolar epithelial cells in allergic asthma." (PMID 33093516, 2020). "The TLR9–IL-2 axis performs a critical effector role to produce the pathology of HDM-induced allergic asthma." (PMID 33093516, 2020). "Here, we induced HDM allergic asthma in Tlr9−/− mice and analyzed their pathology in comparison with that of wild-type (WT) mice." (PMID 33093516, 2020). "To examine that, we analyzed the pathology and immunology of house-dust-mite (HDM)-induced allergic asthma in Tlr9–/– mice and TLR9-inhibitory-antibody-treated mice." (PMID 33093516, 2020). "This suggests that TLR-9 plays an essential part in the modulating A. fumigatus induced allergic asthma." (PMID 31824491, 2019). "In support of this idea, the agonist of TLR9 has been applied to patients in clinical trials for the treatment of allergic asthma by switching Th2 to Th1 immune responses." (PMID 30510553, 2018). "To confirm if TLR signaling had a protective role in our mouse model, we established OVA-induced allergic asthma in tlr2−/−, tlr4−/−, and tlr9−/− mice, and WT mice were used as the control." (PMID 30510553, 2018). "In allergic asthma subjects, TLR9 expression on plasmacytoid dendritic cells and TLR9-induced responses are upregulated by IL-25 that originates from airway epithelial cells." (PMID 27274620, 2016). "Our final conclusion is that TLR9 may be an effective therapeutic target in HDM-induced allergic asthma: treatment with anti-TLR9 inhibitory antibody abruptly increased IL-17A production by interfering with the TLR9–IL-2 axis." (PMID 33093516, 2020). "Our aim was to elucidate the role of the TLR9 response in allergic asthma induced by HDM." (PMID 33093516, 2020). "In addition, we tried to verify the therapeutic effect of TLR9-inhibitory antibodies in HDM-induced allergic asthma." (PMID 33093516, 2020). "In addition, treatment with a novel TLR9 agonist showed clinical efficacy in persistent allergic asthma." (PMID 26380316, 2015). "Moreover, a novel TLR9 agonist showed clinical efficacy in persistent allergic asthma." (PMID 28220116, 2017). "We therefore need to elucidate how HDM-derived DNA or self-DNA is recognized by TLR9 and is involved in the pathology of HDM-induced allergic asthma." (PMID 33093516, 2020). "Allergic asthma was induced with OVA-alum, and the therapeutic effects of anti-TLR7 mAb and anti-TLR9 mAb were determined." (PMID 33093516, 2020). "Similar to the case in the mRNA expression level of IL-5 and IL-13 in allergic asthma, the percentages of IL-5+ and IL-13+ CD4+ Th cells were significantly lower in HDM-sensitized Tlr9−/− mice than in HDM-sensitized WT mice." (PMID 33093516, 2020). "CpG oligodeoxynucleotides (ODNs), which activate TLR9, are the most extensively investigated synthetic TLR agonists in preclinical and clinical studies for the treatment of allergic asthma." (PMID 25019045, 2014). "Here we investigated the role of Toll-Like Receptor 9 in the pathogenesis of allergic asthma without synthesized CpG-ODNs." (PMID 33093516, 2020).
allergic asthma (continued). "Compared with WT mice, tlr2−/−, tlr4−/− but not tlr9−/− mice exhibited increased infiltration of eosinophils in alveoli after allergic asthma establishment." (PMID 30510553, 2018).
B-cell lymphoma (14 papers, 2012 to 2025). "The variant heterozygous genotype of the TLR9 rs5743836 SNP conferred almost a fourfold increased risk of B-cell Non-Hodgkin lymphomas (B-NHL) in patients from Egypt (OR = 3.93, 95% CI = 2.16–7.14)." (PMID 35330409, 2022). "TLR9 rs5743836, polymorphism may represent a molecular risk factor for B-cell Non-Hodgkin lymphomas (B-NHL) among Egyptian subjects." (PMID 35330409, 2022). "For our experiments, we selected the commonly used mouse A20 B cell lymphoma model, which exhibits TLR9 expression and constitutive Stat3 activation." (PMID 39618825, 2024). "In the clinical setting, the abscopal effect has been studied in patients with low grade B cell lymphoma after intratumoral injection of a Toll-like receptor 9 (TLR9) agonist (CpG) during treatment with RT." (PMID 24672524, 2014). "CpG-ODNs are currently being tested in clinical trials for the treatment of non-Hodgkin B-cell lymphoma, which expresses TLR9." (PMID 23561041, 2013). "We show that A20.IIA murine B-cell lymphoma expressed high levels of endogenous TLR9 protein that produced an antiproliferative effect when stimulated in vitro by CpG-ODNs." (PMID 23561041, 2013). "Meanwhile, we analyzed 760 samples of B-cell malignant tumors, and the survival rates of patients with high TLR9 expression were all better than that of patients with low expression, suggesting a close relationship between high TLR9 expression and a good prognosis in patients with B-cell lymphoma." (PMID 38537697, 2024). "In addition, a TLR9 agonist fused to a STAT3 decoy oligodeoxynucleotide (dODN) was also used to inhibit STAT3 in B cell lymphoma." (PMID 37686472, 2023). "Hypothesizing a similar mechanism to human B-cell lymphomas, we can suppose an inhibition of proliferation and induction of apoptosis in TLR9-positive neoplastic cells after treatment." (PMID 35622737, 2022). "Abscopal responses were also reported in a clinical study of patients with low-grade B cell lymphoma treated with 2 Gy × 2 to a single tumor site that was injected with a Toll-like receptor 9 (TLR9) agonist PF-3512676, an activator of B cells and antigen-presenting cells." (PMID 23112958, 2012). "BCAT1 inhibition significantly impaired growth of BCR/TLR9 pathway–dependent MDC DLBCL xenografts in vivo, identifying BCAT1 as a promising B cell lymphoma therapeutic target." (PMID 40924473, 2025). "BCAT1 inhibition significantly impaired growth of BCR/TLR9-pathway dependent MDC DLBCL xenografts in vivo, identifying BCAT1 as a promising novel B-cell lymphoma therapeutic target." (PMID 38854072, 2024). "Carabin has also been demonstrated to be a negative regulator in B-cell activation in SLE and B-cell lymphoma through inhibiting crosstalk between BCR and TLR9 pathways." (PMID 35265067, 2022). "They demonstrate that combination of the TLR9 agonist (CpG) with the STAT3 decoy inhibitor into a single oligodeoxynucleotide conjugate generates two-pronged therapeutic effect by direct and T cell-mediated antitumor effects against B cell lymphoma cells in vivo." (PMID 29433938, 2018).
heart failure (14 papers, 2013 to 2022). Inability of the heart to pump blood at an adequate rate to meet tissue metabolic requirements. "The accumulation of mtDNA into autolysosomes and the co-localization and activation of TLR9 have been observed in DNase II-deficient mice, a model of heart failure, suggesting a relationship between TLR9-induced inflammatory response and disease pathogenesis." (PMID 33802550, 2021). "High levels of ccf-mtDNA have been associated with the development of cardiovascular disease, including atherosclerosis, hypertension, acute myocardial infarction, and heart failure via triggering the TLR9-dependent inflammatory pathway." (PMID 35203322, 2022). "Knockout of TLR9 in the sarcoplasmic/endoplasmic reticulum Ca2+ ATPase 2a (SERCA2a) diastolic heart failure mice reduces their survival." (PMID 33138323, 2020). "A TLR9 inhibitor, E6446, exerted a beneficial effect on attenuating the development or progression of heart failure in a pressure overload–induced mouse model." (PMID 31312759, 2019). "Based on our data showing the importance of TLR9 signaling in the development of inflammation and heart failure and its specificity to TLR9 in cardiomyocytes, the cardioprotective action of E6446 is TLR9 mediated." (PMID 31312759, 2019). "When E6446 was orally administered to mice before TAC, E6446 inhibited TLR9 signaling by interfering with the mitochondrial DNA−TLR9 interaction and subsequent development of inflammation and heart failure." (PMID 31312759, 2019). "Insufficient degradation of mitochondrial DNA mediated through autophagy in pressure-overloaded mouse hearts leads to its binding to TLR9 to induce inflammation and heart failure." (PMID 31312759, 2019). "Mitochondrial deoxyribonucleic acid, containing the unmethylated cytidine-phosphate-guanosine motif, stimulates Toll-like receptor 9 to induce inflammation and heart failure." (PMID 31312759, 2019). "•Under pressure overload, mitochondrial deoxyribonucleic acid containing the unmethylated cytidine-phosphate-guanosine motif is accumulated in cardiomyocytes and stimulates Toll-like receptor 9, resulting in inflammation and heart failure." (PMID 31312759, 2019). "E6446 prevents cellular events activated by TLR9, exerting broader inhibitory effects on inflammatory cytokine production, and thus the treatment of heart failure with the inhibitor has an advantage over the therapy neutralizing only 1 cytokine." (PMID 31312759, 2019). "Toll-like receptor 9 plays animportant role in the development of stress-induced inflammation and heart failure." (PMID 29658970, 2018). "Deletion of Tlr9 in mice results in the attenuation of inflammation and cardiac dysfunction in a pressure-overload-induced heart failure model." (PMID 29511093, 2018). "The involvement of mtDNA in cardiac inflammation is clearly demonstrated in this model, and a loss of sensing of mtDNA from damaged mitochondria in autolysosomes during mitophagy by TLR9 leads to the inactivation of the innate immunity in heart failure." (PMID 29511093, 2018). "Finally, EVs can transfer mtDNA from T lymphocytes to dendritic cells to trigger an inflammatory response via the toll-like receptor-9 (TLR-9)−nuclear factor kappa B (NF-κB) pathway in patients with heart failure." (PMID 35203322, 2022). "Thus, investigation of the involvement of the TLR9-signaling pathway in other mouse or larger animal heart failure models and various types of human heart failure is warranted." (PMID 31312759, 2019). "We ultimately will be able to identify subsets of patients with heart failure who will benefit from inhibition of TLR9 signaling.PerspectivesCOMPETENCY IN MEDICAL KNOWLEDGE: Heart failure is a major health threat in the developed countries with high morbidity and mortality." (PMID 31312759, 2019). "Furthermore, TLR9 ablation in pressure-overloaded mice attenuated the development of inflammation and heart failure." (PMID 31312759, 2019).
heart failure (continued). "However, results from studies investigating the role of TLR9 in pressure-overload induced heart failure are ambiguous, as both beneficial and harmful effects of TLR9-activation have been shown." (PMID 25126740, 2014). "There are contrasting results regarding the consequence of TLR9-stimulation in heart failure." (PMID 25126740, 2014).
parasitemia (14 papers, 2011 to 2025). "TLR9 engagement is involved in trypanosomosis associated IFNγ induction as well as parasitemia control of T. b." (PMID 34762705, 2021). "Monocytes and monocyte derived DCs have also been strongly implicated in the regulation of Th1 immunity to parasite infections that trigger TLR9." (PMID 28729715, 2017). "Allelic variants in the promoter region of TLR9 -1237C/T and -1486C/T are associated with parasitemia in Pf-infected individuals and placental malaria." (PMID 28850598, 2017). "Although depression of MHC-I, IFNs and TLR9 genes is commonly associated with immune system evasion by viruses, the importance of this mechanism in parasite infections is becoming increasingly evident." (PMID 25526753, 2014). "By studying a Plasmodium chabaudi chabaudi AS (PcAS) malaria infection in mice bearing a TLR9 null mutation, we found an increased susceptibility to infection, i.e. higher parasitemia levels and increased mortality." (PMID 22096530, 2011). "Association of genotypic frequencies of TLR9 gene SNPs with parasitemia." (PMID 40587574, 2025). "TLR9-depleted mice showed loss in control of parasitic infections compared to wild type mice." (PMID 28850598, 2017). "Furthermore, the TLR9 variant -1237C/C correlates with high parasitemia." (PMID 28850598, 2017). "Furthermore, the SNP TLR9 -1237C/T was associated with increased parasitemia." (PMID 28850598, 2017). "Fever (COEF = 7599.46, 95% CI = 3063.80–12135.12, p = 0.001) and the C/C genotype of TLR9 -1237C/T (COEF = 17006.63, 95% CI = 3472.83–30540.44, p = 0.014) were independently associated with increased parasitemia." (PMID 28850598, 2017). "Given the potential application for TLR-ligands such as CpG motifs to act as adjuvants in vaccination strategies this study assesses if resistance to L. guyanensis parasite infection is mediated by MyD88, and TLR9." (PMID 24801628, 2014). "In this regard, the role of TLRs has been investigated; TLR9 was shown to be crucial in the parasitemia control and mouse survival, whereas TLR2 was defined as immunoregulator." (PMID 23650544, 2013). "Haemozoin is a dark-brown haem crystal produced by P. falciparum that functions as a carrier for P. falciparum DNA and functionally affects TLR9 response to parasite infection activating TLR9 proportionally to its concentration." (PMID 22691414, 2012). "We did not observe an association between parasitemia and the evaluated SNPs of the TLR9 gene, similar to those reported in the Brazil-French Guiana border." (PMID 40587574, 2025). "Thus, our data extend previous studies, demonstrating that rfd phages induce Ag-specific IgG and CD8+ T cell-mediated responses and confer protection against an important human parasite infection, through a TLR9-dependent mechanism." (PMID 29896197, 2018). "Hence, although discrepant from other published data, the B6.TLR9−/−(OR) mice were less well protected against acute and chronic parasitemia." (PMID 22096530, 2011). "The data presented in this study highlight the importance of a well-defined homogenous genetic background - which should be as similar as possible between the control and the mutant line - in the analysis of the effect of a TLR9 deletion on the parasitemia course during a PcAS infection." (PMID 22096530, 2011). "Here we analyzed the requirement of TLR2 and TLR9 in the release of TNF-α, IL-12/IL-23p40 and IFN-γ, all present before the peak of parasitemia." (PMID 23650544, 2013). "Although vaccination with rfd phages successfully reduced both parasitemia and parasite load in the myocardium of WT B6 mice, Tlr9−/− animals were not protected against infection." (PMID 29896197, 2018). "In fact, TLR4 and TLR9 pathways, other than the TLR2 signal, can promote iNOS/NO production and play an important role in modulating injured livers from BALB/c and C57BL/6 mice during parasitic infection." (PMID 28784165, 2017).
parasitemia (continued). "TLR2 does not affect the parasitemia and mortality, whereas TLR9 appears to be crucial for the control of parasite replication and mouse survival." (PMID 23650544, 2013). "On the other hand, immunization was not able to reduce parasitemia levels in Tlr9−/− mice." (PMID 29896197, 2018). "According to our data, the establishment of Th1 response depends on TLR9, but not on TLR2, which corroborates with evidence identifying the involvement of TLR9 in controlling parasitemia and survival during primary infection with T. cruzi." (PMID 23650544, 2013).